PSME2 (proteasome activator subunit 2)
Diseases named in the same sentence as PSME2 in open-access papers (continued):
Sharing a sentence is not in itself a finding about the gene and the disease.
cancer (22 papers, 2006 to 2025). A tumor composed of atypical neoplastic, often pleomorphic cells that invade other tissues. "Our identification of PSME2 as a gene with high diagnostic efficacy mirrors findings from other studies highlighting its role in cancer biology." (PMID 41403941, 2025). "A growing number of studies have revealed an association between proteasome activator complex subunit 2 (PSME2) and the progression of various forms of cancer." (PMID 38385075, 2024). "This provides a direction for subsequent investigations into the mechanisms underlying the role of PSME2 in cancer." (PMID 38385075, 2024). "Subsequently, the association between PSME2 expression levels and chemotherapy response in cancer was assessed using ROCplotter." (PMID 38385075, 2024). "In addition, increased expression of PSME2 is associated with cancer invasion through the regulation of autophagy." (PMID 38774969, 2024). "We found that low intratumor LMP2, PSME1 and PSME2 expression predicted a good response to NACI in cancer patients." (PMID 41035633, 2025). "We further analyzed the expression of proteins LMP2, PSME1, and PSME2 in cancer and normal tissues, involving pathological staging." (PMID 41035633, 2025). "Significant PSME2 dysregulation was noted in a wide range of cancer types and this gene was found to offer significant diagnostic and prognostic utility in most analyzed cancers." (PMID 38385075, 2024). "This suggests that higher PSME2 levels in most cancers coincide with higher TMB and MSI levels, contributing to improved therapeutic outcomes following the administration of immunotherapeutic agents." (PMID 38385075, 2024). "Here, a positive association was noted between PSME2 expression and TMB, MSI, and immune checkpoint expression in most analyzed cancer types." (PMID 38385075, 2024). "Single-cell transcriptional data from TISCH additionally confirmed the expression of PSME2 in M1 macrophages and malignant tumor cells in most analyzed cancer types." (PMID 38385075, 2024). "The results indicated the potential involvement of PSME2 in multiple oncogenic pathways in a variety of cancers." (PMID 38385075, 2024). "The Cancer Genome Atlas and Genome-Tissue Expression databases were leveraged to evaluate PSME2 expression and activity across 33 cancer types." (PMID 38385075, 2024). "There is thus a pressing need to examine the important roles that the expression of PSME2 plays in many different forms of cancer in order to inform future experimental and clinical research efforts." (PMID 38385075, 2024). "The TCGA and GTEx databases were initially used to conduct a systematic pan-cancer analysis of the expression of PSME2 at the mRNA level." (PMID 38385075, 2024). "When evaluating six different therapeutically relevant tumor types, high levels of PSME2 expression tended to be evident in cancers of the IFN-γ-dominated C2 subtype." (PMID 38385075, 2024). "Together, these analyses suggested a role for PSME2 in DNA methylation and mRNA modification in a range of cancer types." (PMID 38385075, 2024). "This strongly supports a role for PSME2 as a regulator of antitumor immunity in many types of cancer." (PMID 38385075, 2024). "TIMER2.0 analyses revealed a positive correlation between M1 macrophage infiltration and PSME2 expression levels across cancers, while a low correlation was found with PSME2 promoter methylation." (PMID 38385075, 2024). "PSME2 was subsequently established as a pan-cancer biomarker of M1 macrophage infiltration based on a combination of bulk, single-cell, and spatial transcriptomic data and confirmatory fluorescent staining results." (PMID 38385075, 2024). "Screening efforts were also used to identify PSME2-activating drugs with potential value for use in specific forms of cancer." (PMID 38385075, 2024). "Building on these prior reports, the present study was conducted to systematically analyze the expression, prognostic relevance, and functions of PSME2 across cancer types." (PMID 38385075, 2024).
cancer (continued). "In particular, these analyses centered around DNA repair, DNA damage, and the induction of cancer-related immune responses, with subsequent confirmation of the identification of PSME2 as a biomarker of M1 macrophage infiltration through fluorescent staining." (PMID 38385075, 2024). "There are contradictory data on the role of proteasome activator subunit 2 (PSME2) in cancer progression." (PMID 37529110, 2023). "PSME2, although little studied in BC, has been found to have anticancer effects in a variety of cancers." (PMID 36226063, 2022). "In this study, we used the BrCa cohort from the Cancer Genome Atlas (TCGA) dataset to investigate the expression and immunological characteristics of PSME2 in BrCa." (PMID 36583022, 2022). "The expression of PSME1 and PSME2 was positively correlated with the infiltration of most immune cells and the activation of anti-cancer immunity cycle steps." (PMID 34650966, 2021). "Similar to PSME1, our study found that the expression of PSME2 was positively correlated with the infiltration of most immune cells and the activation of anti-cancer immunity cycle steps." (PMID 34650966, 2021). "Mechanistically, PSME2 is negatively regulated by the N-α-acetyltransferase 10 protein to regulate multiple pathways related to cancer cell proliferation, apoptosis, and metastasis." (PMID 34650966, 2021). "Therefore, we conclude that low intratumoral expression of LMP2, PSME1 and PSME2 predicts a good response to NACI in cancer patients." (PMID 41035633, 2025). "Together these results suggest that PSME2 AS events may have important implications for the progression of many cancers." (PMID 38385075, 2024). "This dual role of PSME2 may be attributed to the activation of distinct molecular pathways in different cancer types, underscoring the inherent complexity and heterogeneity characteristic of cancer biology." (PMID 38385075, 2024). "PSME2 was also identified as a potential pan-cancer biomarker for M1 macrophage infiltration." (PMID 38385075, 2024). "This approach revealed differential PSME2 expression in 24 cancer types." (PMID 38385075, 2024). "Here, a poly-omics pan-cancer study of PSME2 was conducted using an integrated series of tools and datasets corresponding to different cancers and normal tissues in an effort to clarify the relationships between this gene, clinical characteristics, and multi-omic heterogeneity." (PMID 38385075, 2024). "The bulk, spatial, single-cell transcriptional data and the fluorescence staining results above highlight the close relationship between PSME2 expression and M1 macrophages, suggesting that PSME2 may be a pan-cancer biomarker of M1 macrophage infiltration." (PMID 38385075, 2024). "Previous studies also reported the immuno-correlated role of PSME2 in other cancers." (PMID 36583022, 2022). "Overall, PSME2 was tightly immuno-correlated in not only BrCa, but also multiple cancer types, which may be a pan-cancer biomarker." (PMID 36583022, 2022). "Increasing evidence supports the dual functionality of specific genes, including KLF4, PSME2, and TGF-β, as both oncogenes and tumor suppressors, depending on cancer type and stage." (PMID 41235100, 2025). "From a mechanistic perspective, PSME2 expression levels were correlated with DNA methylation, DNA repair, genomic instability, and TME scores in multiple cancer types." (PMID 38385075, 2024). "The genes categorized into “cancer” group by IPA biofunctions analysis were GPX1, HDAC7, PSME2, MED6, GOLPH3 and MST4 (p<0.05)." (PMID 22438889, 2012). "Additionally, PCR results reveal that PSME2 and PSMB8 are highly expressed in cancer tissues, while BMP5 and BCL2 are more highly expressed in normal tissues." (PMID 41403941, 2025). "Differential PSME2 expression in various immunological cancer subtypes was further assessed with TISIDB, revealing a significant relationship between PSME2 levels and immune subtypes for 23 cancer types." (PMID 38385075, 2024).
cancer (continued). "This contrasts with our finding, perhaps PSME2 and EVA1B possess cancer specific, and whether the regulation of these two genes also involves autophagy and tumor immune regulation in this study remains to be further explored." (PMID 36267313, 2022). "In this study, we first demonstrated the relationship among PSMB8, PSMB9, PSMB10, PSME1, PSME2, and IRF1 in the immune micro-environment and immune score through TCGA whole cancer cohorts, and further, we proved the correlation between PSMB8, PSMB9, PSMB10, PSME1, PSME2, IRF1, and immune cells." (PMID 36700205, 2022).
tumor (20 papers, 2016 to 2025). "Moreover, GC patients with high PSME1 and PSME2 expression have higher immunophenoscore and tumor mutational burden." (PMID 34650966, 2021). "We analyzed the role of ICDRs in tumor immune microenvironment by using the previous data of single cell transcriptome, and we analyzed the distribution of several key genes (PSME2, TYMP, KLHDC7B, GBP5, EPSTI1, STAT1 and OAS2) in different cell types." (PMID 40259929, 2025). "We performed IHC to examine the expression levels of LMP2, PSME1 and PSME2 in NACI-NSCLC tumor tissue samples before NACI, and to explore their prognostic value in patients with NACI-NSCLC." (PMID 41035633, 2025). "To verify the specific role of macrophage and tumor cell polyamine metabolism in tumor progression, we detected the levels of PSME2 and PSMA2 in early THCA and locally invasive THCA tissue samples." (PMID 40390766, 2025). "In this study, we examined the expression of LMP2, PSME1, and PSME2 in pre-treatment NACI-NSCLC tumor tissue specimens and explored their prognostic value in patients with NACI-NSCLC." (PMID 41035633, 2025). "Protein expression of LMP2, PSME1, and PSME2 was assessed by immunohistochemistry (IHC) in pre-treatment tumor biopsies from a retrospective cohort of 50 resectable NSCLC patients treated with NACI (platinum-based chemotherapy + anti-PD-1/PD-L1)." (PMID 41035633, 2025). "In vivo, PSME2 overexpression also suppressed subcutaneous xenograft tumor growth relative to control tumors." (PMID 38385075, 2024). "PSME2 expression was also evaluated in 33 tumor types across a range of clinical stages, subtypes, and TNM stages." (PMID 38385075, 2024). "Of these compounds, 6 were topoisomerase inhibitors, suggesting a close link between PSME2 and specific mechanisms within tumor cells." (PMID 38385075, 2024). "GSEA results in the present study also supported the potential ability of PSME2 to influence tumor development or progression by regulating IFN-α and IFN-γ responses." (PMID 38385075, 2024). "Three tumor-associated antigens, CD74, IRF1, and PSME2, that showed overexpression, amplification, and mutation and were linked with prognosis and immune cell infiltration, were identified." (PMID 36226063, 2022). "Patients with higher levels of tumor-associated CD74 had significantly better outcomes in comparison with those with lower levels and high levels of IRF1 and PSME2 were also linked with better prognosis." (PMID 36226063, 2022). "Overall, PSME2 expression is increased in BrCa compared with para-tumor tissues, but predicts well prognosis in BrCa." (PMID 36583022, 2022). "We used the BrCa cohort from the TCGA dataset to compare the mRNA levels of PSME2 between BrCa and para-tumor breast tissues." (PMID 36583022, 2022). "We found that HSPA5 and PSME2 were significantly upregulated whereas HLA-F was significantly downregulated in tumor tissues compared with normal tissue (p < 0.0001)." (PMID 34257557, 2021). "Since our analysis above revealed that LMP2, PSME1 and PSME2 might play a role in antitumor immunity, we established a retrospective tumor cohort (validation cohort) of 50 patients with NSCLC treated with NACI to further examine our findings." (PMID 41035633, 2025). "This further strengthens the inference that PSME2 may influence therapeutic response by modulating the tumor immune microenvironment." (PMID 41403941, 2025). "As OV patients with low levels of PSME2 expression responded poorly to routine chemotherapy, the possibility that the PSME2-activating medication irinotecan may increase tumor chemosensitivity was investigated." (PMID 38385075, 2024). "PSME2 was additionally positively correlated with tumor stemness in CHOL." (PMID 38385075, 2024). "However, recent evidence suggests that PSME2 plays a valuable role in regulating tumor development and the presentation of tumor-derived antigens." (PMID 38385075, 2024). "The result confirmed that expression of PSME2 in BrCa was higher than that in para-tumor tissues." (PMID 36583022, 2022).
tumor (continued). "This suggests that PSME2 may be involved in antigen processing and presentation in the BC tumor microenvironment." (PMID 36226063, 2022). "PSME2 is significantly down-regulated in esophageal carcinoma tissues compared to normal tissues and could act as a potential tumor inhibitor." (PMID 34650966, 2021). "Finally, with a deeper understanding of the molecular mechanisms underlying the formation, function, and therapeutic benefits of LMP2, PSME1, and PSME2 in the tumor, it may help guide NACI’s strategies for personalized precision medicine in the future." (PMID 41035633, 2025). "The results show that the low expression of LMP2, PSME1, and PSME2 within the tumor is significantly correlated with a good pathological response (MPR) of patients to NACI, suggesting that they may influence treatment sensitivity by regulating antigen presentation and the immune microenvironment." (PMID 41035633, 2025). "While our study established associations between LMP2, PSME1, PSME2 expression (via transcriptomic/database analysis and IHC in a clinical cohort) and NACI response/survival outcomes, the IHC correlations do not establish a causal role for these immunoproteasome subunits in anti-tumor immunity." (PMID 41035633, 2025). "The results indicated a consistent decrease in BCL2 and BMP5 expression in most tumor samples, while PSMB8 and PSME2 showed increased expression." (PMID 41403941, 2025). "PSME2 was down-regulated at the mRNA level and up-regulated at the protein level in OV, LUAD, LIHC, and GBM tumor tissues compared to corresponding normal tissues." (PMID 38385075, 2024). "In addition, increasing numbers of studies showed that PSME2 may be used as a tumor biomarker." (PMID 36583022, 2022). "PSMB8, PSMB9, PSMB10, PSME2, TAP1, and IRF1 promote CD8+ T cell infiltration by enhancing MHC class I tumor antigen processing." (PMID 33330025, 2020). "Tumor samples were collected from the patients before receiving NACI treatment, and the Intratumoral proportion and expression intensity of LMP2, PSME1 and PSME2 was evaluated by performing IHC." (PMID 41035633, 2025). "Such a mechanism for the PSME2-mediated regulation of tumor development has not previously been reported, highlighting a promising avenue for future study." (PMID 38385075, 2024). "In the present study, we demonstrated that PSME2 expression was significantly increased in GC tumor tissues compared to non-cancerous tissues." (PMID 34650966, 2021). "TAP2 (P < 0.001; Cor = 0.60), PSME2 (P < 0.001; Cor = 0.52), HLA - E (P < 0.001; Cor = 0.69), and LCK (P < 0.001; Cor = 0.69) positively related to CD8+ T cell and negatively correlated with tumor purity." (PMID 33692827, 2021). "Eight co-expressed genes (PSMB8, PSMB9, PSMB10, PSME2, TAP1, IRF1, FBOX6, ETV7) were identified as CD8+ T cell-related genes that promoted infiltration of CD8+ T cells, and were enriched in the MHC class I tumor antigen presentation process." (PMID 33330025, 2020).
infection (7 papers, 2012 to 2023). The state of being infected such as from the introduction of a foreign agent such as serum, vaccine, antigenic substance or organism. "In blood neutrophils, in the steady state (e.g. Myc, H2-DMb2, H2-M3, H2-Q7...) but also during infection e.g. Cxcl10, H2-D1, C4a, Psme1, Stat1, Psme2, more genes were upregulated in neutrophils from female mice." (PMID 38179044, 2023). "In fact, we only observed two exceptions to this classification at 24 h post-infection: Psme2 (more induced in mutants than in controls), and Samsn1 (repressed in controls, and unaffected in mutant cells)." (PMID 22916300, 2012).
PSME2 also shares sentences with these, for which no sentence is quoted: bacterial disease (2 papers); bladder cancer (2); glioma (2); breast tumor (1); Burkitt lymphoma (1); colorectal cancer (1); COVID-19 (1); Hypertension (1); Immunodeficiency (1); kidney cancer (1); liver cancer (1); malignant skin tumors (1); neurodevelopmental disorder (1); non-small cell lung carcinoma (1); ovarian carcinoma (1); skin cutaneous melanoma (1); viral myocarditis (1).